LRP5 (LDL receptor related protein 5)
Diseases named in the same sentence as LRP5 in open-access papers (continued):
Sharing a sentence is not in itself a finding about the gene and the disease.
osteoporosis (continued). "Of these, only ESR1 and LRP5 have shown to be effectively contributing to explain population variance in risk for osteoporosis." (PMID 33162933, 2020). "Recently, some findings have demonstrated that polymorphisms in the estrogen receptor (ER), type I collagen (COL1), vitamin D receptor, and low density lipoprotein receptor-related protein 5 (LRP5) genes are highly associated with osteoporosis." (PMID 33315972, 2020). "It's worth mentioning that a loss and a gain of the function mutations in the LRP5 would both lead to osteoporosis-pseudoglioma syndrome and high bone mass conditions." (PMID 30842754, 2019). "Vitamin D receptor (VDR), Type I collagen (COL1), estrogen receptor (ER), apolipoprotein E (ApoE), bone morphogenetic protein (BMP), LRP5 genes and polymorphisms have been also proved to be involved in osteoporosis etiology." (PMID 31113874, 2019). "Teriparatide treatment increases bone mass in Lrp5 KO mice mimicking humans with osteoporosis pseudoglioma syndrome from loss of function LRP5 mutations." (PMID 32117046, 2019). "The mutation of LRP5 has been said to be associated with osteoporosis and the change in bone mass syndrome." (PMID 31031810, 2019). "On the other hand, the LRP5 4037C>T is recognized as one of the key polymorphism in associated with increase the risk of bone fracture and osteoporosis, as well as in the cardiovascular diseases." (PMID 30304114, 2018). "Several common genetic variants of LRP5 gene have been demonstrated as potential risk factors in osteoporosis and fracture by previous GWAS." (PMID 30159320, 2018). "This way, LRP5 gene plays a key role in bone homeostasis and several skeletal pathologies, such as osteoporosis, are related to mutations in its coding region." (PMID 29123202, 2017). "Loss-of-function mutations in the Wnt-binding co-receptor LRP5 leads to aberrant ocular vascularization and loss of vision in genetic disorders such as osteoporosis-pseudoglioma syndrome." (PMID 27031698, 2016). "have studied single cases and found three different LRP5 variants in two women with pregnancy-related osteoporosis and vertebral fractures, and one boy with idiopathic juvenile osteoporosis." (PMID 27533615, 2016). "A derived missense variant (rs3736228; p.Ala1330Val) in LRP5 is of particular interest due to its association with bone mineral density and osteoporosis (OMIM: 166710)." (PMID 26719974, 2015). "In mammals, Lrp5 plays a major role in bone homeostasis, and mutations in LRP5 are associated with reduced bone mass leading to the osteoporosis-pseudoglioma syndrome in humans." (PMID 26121341, 2015). "Nowadays, there was no meta-analysis focused on the relationships between polymorphism rs3736228 C>T in the LRP5 gene and the risk of bone fracture, as well as osteoporosis." (PMID 25580429, 2014). "In this meta-analysis, one SNP within the LRP5 gene was identified, and the association between the allelic and genotypic frequencies of LRP5 rs3736228 C>T and the risk of osteoporosis and fractures were investigated." (PMID 25580429, 2014). "The information of the SNPs (rs3736228 C>T) in the LRP5 gene was included to evaluate the association between polymorphic variants of the LRP5 gene and the risk of osteoporosis and fractures." (PMID 25580429, 2014). "The present study was aimed at examining the association of LRP5 rs3736228 C>T gene with bone fracture and osteoporosis by meta-analysis." (PMID 25580429, 2014). "While inactivating mutations in LRP5 were shown to cause osteoporosis-pseudoglioma syndrome, gain-of-function mutations caused a high bone mass (HBM) phenotype." (PMID 24736728, 2014). "LRP5 gain of function results in increased bone mass, whereas mutations in the gene encoding for LRP5 causes osteoporosis-pseudoglioma syndrome." (PMID 24865492, 2014). "Recently, genetic variants in the LRP5 gene have been reported to be associated with the risk of bone fracture and osteoporosis." (PMID 25580429, 2014).
osteoporosis (continued). "Ethnicity-subgroup analysis implied that LRP5 rs3736228 C>T mutation was more likely to develop osteoporosis and fractures among Asians and Caucasians in majority of subgroups." (PMID 25580429, 2014). "More specifically, it was found that inactivating mutations of the human LRP5 gene cause osteoporosis-pseudoglioma syndrome, a rare genetic disorder characterized by impaired bone formation and persistence of hyaloid vessels in the eyeballs." (PMID 26056589, 2014). "Lrp 5 deficiency (Lrp5−/−) as well as osteoblast-specific overexpression of Krm2 in mice (Col1a1-Krm2) result in severe osteoporosis occurring at young age." (PMID 25061805, 2014). "A systematic electronic search of literature was conducted to identify all published studies in English or Chinese on the association of the LRP5 gene with bone fracture and osteoporosis risks." (PMID 25580429, 2014). "All HBM-related LRP5 mutations identified to date are located in the first beta-propeller of the protein, while the mutations that cause osteoporosis-pseudoglioma syndrome and exudative vitreoretinopathy are found all over the gene." (PMID 24736728, 2014). "Inactivating mutations of LRP5 induce the osteoporosis-pseudoglioma syndrome in humans, whereas gain-of-function mutations of LRP5 result in a high bone mass phenotype because of increased osteoblast activity." (PMID 24391920, 2013). "Activating mutations in lipoprotein receptor-related protein 5 (LRP5), a Wnt co-receptor, induce high bone mass phenotype, whereas inactivating mutations cause osteoporosis-pseudoglioma syndrome, characterized by osteoporosis and blindness." (PMID 24066100, 2013). "Inactivating mutations of the LRP5 Wnt coreceptor cause osteoporosis, indicating that Wnt-mediated signaling via LRP5 affects bone accrual during growth and is important for the establishment of peak bone mass." (PMID 23766767, 2013). "Mutation of LRP5 results in osteoporosis and increased bone mass syndrome, whereas conditional deletion of the LRP5 gene in mice results in enhanced bone formation." (PMID 24403228, 2013). "Rs3736228 located in 11q13.2 site belongs to LRP5 gene, and LRP5 gene has been confirmed by more research as osteoporosis susceptibility genes." (PMID 24278256, 2013). "The present work provides further proof of the role of LRP5 in the disorder by revealing two additional heterozygous missense mutations (L1149Q and G1185R) in patients with primary osteoporosis." (PMID 22487062, 2012). "LRP5-activating mutations are mainly associated with high-bone mass, while loss-of-function mutations on LRP5 are linked to bone degeneration and osteoporosis." (PMID 27398238, 2012). "All LRP5 mutations associated with primary osteoporosis in our patient set (A29T, C913fs, R1036Q, L1149Q, G1185R) are located in the coding regions of the LRP5 gene." (PMID 22487062, 2012). "We identified enhanced expression of 39 genes in hMSC-OP and reduced expression of 16 genes that are already described as reliable or promising candidates for osteoporosis, including susceptibility genes like LRP5, SPP1 (Osteopontin), COL1A1 and SOST." (PMID 23028809, 2012). "A loss or gain of function in the Wnt coreceptor LRP5 is associated with osteoporosis or high bone mass, respectively." (PMID 20043861, 2010). "Inactivating mutations of LRP5 lead to osteoporosis pseudoglyoma while activating mutations result in high bone mass phenotypes." (PMID 20948561, 2010). "A systematic electronic search of literature was conducted to identify all published studies in English on the association between LRP5 gene and osteoporosis-related phenotypes, including bone mineral density and fracture." (PMID 18588671, 2008). "The electronic search yielded 65 papers on the association between LRP5 and osteoporosis-related phenotypes; however, only 19 met the inclusion criteria." (PMID 18588671, 2008).
osteoporosis (continued). "Loss of function mutations in human LRP5 are associated with osteoporosis-pseudoglioma syndrome, which causes low bone mass and skeletal fragility." (PMID 17295923, 2007). "Several mutations of LRP5 known to cause osteoporosis-pseudoglioma syndrome is located within amino acids 666–809, highlighting a functional role for this part of the protein." (PMID 18044981, 2007). "Interestingly, heterozygous dominant mutations in WNT1 cause early-onset osteoporosis; likewise, mutations in LRP5 result in both dominant and recessive forms of osteoporosis." (PMID 41410595, 2025). "The discovery of biallelic loss-of-function mutations in the LRP5 gene in osteoporosis-pseudoglioma, an autosomal recessive disease characterized by loss of osteoblast function and thus low bone mass demonstrated the importance of the Wnt co receptor LRP5 in bone remodeling." (PMID 40115506, 2025). "Furthermore, several genome-wide association studies (GWASs) have identified LRP5 as a key risk locus for osteoporosis-related traits." (PMID 39791729, 2024). "In particular, loss-of-function mutations in the WNT co-receptor LRP5 (low-density lipoprotein receptor-related protein 5) result in low bone mass in osteoporosis-pseudoglioma syndrome, whereas gain-of-function mutations in LRP5 markedly increase bone mass in otherwise healthy individuals." (PMID 39434845, 2024). "The clinical, radiographic and bone densitometry patterns, however, may overlap with Osteogenesis Imperfecta type 5 and familial forms of osteoporosis, such as heterozygous LRP5 variants and hemizygous PLS3 variants." (PMID 38942908, 2024). "Mutations and polymorphisms related to osteoporosis have also been identified at the low-density lipoprotein receptor-related protein 5 (LRP-5) gene, which maps to chromosome 11q12-q13 and at the Osteoprotegerin gene, which is a soluble protein receptor for RANKL." (PMID 35163424, 2022). "In patients with osteoporosis-pseudoglioma syndrome due to biallelic LRP5 variants the response to bisphosphonate treatment is usually good, but little is known about the treatment responses in those harboring heterozygous LRP5 variants." (PMID 34236445, 2022). "In addition, the aberrant regulation of Wnt inhibitors such as Sclerostin (SOST) and Dickkopf (DKK), which bind to LRP5/6, was found to cause different bone diseases, such as sclerosteosis and osteoporosis." (PMID 36497192, 2022). "In some patients an underlying genetic predisposition may be identified, e.g., with pathogenic variants in LRP5, suggesting a pre-existing monogenetic form of osteoporosis with an exacerbation due to pregnancy, resulting in vertebral fractures." (PMID 34236445, 2022). "Loss of function mutations in the Wnt co-receptor LRP5 results in severe osteoporosis." (PMID 34020675, 2021). "Similar to WNT1, biallelic loss of function mutations in its co-receptor LRP5 cause osteoporosis-pseudoglioma syndrome, which is characterized by severe bone fragility and ocular manifestations, and monoallelic LRP5 mutations, which cause primary, autosomal dominant osteoporosis." (PMID 33435159, 2021). "The precision care included cryotherapy to prevent retinal detachment in COL2A1 Stickler syndrome, osteoporosis management in patients with LRP5-associated familial exudative vitreoretinopathy, and avoidance of unnecessary phlebotomy in hyperferritinemia-cataract syndrome." (PMID 35052368, 2021). "In addition, it has been reported that the LRP5 4037C>T is associated with susceptibility to type 2 diabetes mellitus and osteoporosis in postmenopausal women." (PMID 30304114, 2018). "Moreover, polymorphisms and mutations in the LRP5 are associated with osteoporosis, impaired glucose, increased risk for obesity, type 2 diabetes mellitus, and other metabolic diseases." (PMID 30304114, 2018).
osteoporosis (continued). "Further functional study on the molecular mechanism of CPT1A, MTL5 gene and LRP5 rs3736228 may help us comprehend the association between osteoporosis and candidate gene, understand the pathogenesis of osteoporosis and the genetic mechanism." (PMID 28369098, 2017). "Clinically, miR-375-3p and its targets LRP5 and β-catenin might be used as diagnostic biomarkers for osteoporosis, osteoarthritis or osteosarcoma because they regulate or disturb osteogenesis." (PMID 28158288, 2017). "We speculate that this SNP may influence osteoporosis risk through changing the amino acid sequence and secondary structure of the LRP5 protein." (PMID 28369098, 2017). "Genetic variations at the LRP5 gene locus are associated with osteoporosis, which suggests that genetic variations in Wnt signaling genes may affect the pathogenesis of osteoporosis." (PMID 27119226, 2016). "Further studies have associated LRP5 variants with an array of extreme osteoporosis phenotypes." (PMID 27533615, 2016). "In 2001, the breakthrough discovery of the involvement of the Wnt signalling pathway on the regulation of bone remodelling was made possible by the study of rare conditions such as osteoporosis-pseudoglioma syndrome (OPPG) due to LRP5 mutations and sclerosteosis due to SOST defects." (PMID 27533615, 2016). "LRP5 HBM-causing mutations are of particular therapeutic interest as they may hold clues for effective treatments for osteoporosis and disuse-induced bone loss." (PMID 26554834, 2015). "From the 7 included studies, 2 studies focused on the genotype/allele frequencies of LRP5 (rs3736228 C>T) in fracture patients and the controls; the other 5 studies were concerned about the genotype/allele frequencies of LRP5 (rs3736228 C>T) in osteoporosis patients and the controls." (PMID 25580429, 2014). "In conclusions, the Ala1330Val variant seems to be weakly associated with lower lumbar spine BMD in Tunisian post-menopausal women, contributing to the notion that LRP5 genetic variation is a ubiquitous determinant of osteoporosis risk among various ethnicities." (PMID 24885293, 2014). "The present meta-analysis aggregated large-scale evidence from relevant studies in an attempt to determine whether rs3736228 C>T polymorphism in the LRP5 gene was related with susceptibility to bone fracture and osteoporosis." (PMID 25580429, 2014). "A few common polymorphisms of the LRP5 gene have been detected in correlation with bone phenotypes, including fracture risk and BMD, among which a coding single nucleotide polymorphism (SNP) of the LRP5 gene, rs3736228 (A1330V), is thought to have a particular susceptibility to osteoporosis." (PMID 25580429, 2014). "In 2001, Lrp5, and thereby Wnt signaling, entered center stage in the research area of bone remodeling, a homeostatic process controlling bone mass, whose disturbance causes osteoporosis, one of the most prevalent disorders worldwide." (PMID 26056589, 2014). "In summary, this meta-analysis suggests that rs3736228 C>T variant in the LRP5 gene may increase the risk of bone fracture and osteoporosis." (PMID 25580429, 2014). "Finally, the present sample size did limit the power to identify LRP5 rs3736228 polymorphism with a small influence on bone fracture and osteoporosis." (PMID 25580429, 2014). "Recently, many studies have emphasized exploring the relationships of clinical biomarkers with bone fracture and osteoporosis, and lipoprotein receptor-related protein 5 (LRP5), whose mutations would reduce bone mineral density, is thought to be corrected with the susceptibility to osteoporosis." (PMID 25580429, 2014). "Loss-of-function mutations in LRP5 reduce the number of osteoblasts and cause osteoporosis." (PMID 23710175, 2013).
osteoporosis (continued). "Recently performed genome-wide-association studies (GWAS) have confirmed many previously identified candidate genes for osteoporosis, such as LRP5, OPG, RANK, and RANKL, and polymorphisms affecting the expression of these gene products have implications on bone mass and strength." (PMID 22773251, 2013). "Our in vitro studies with four LRP5 mutations causing primary osteoporosis showed that all the LRP5 constructs were able to mediate signaling and that the signaling activity was enhanced several-fold in all the constructs when Wnt3a was added, supporting the role of Wnt3a as a ligand for LRP5." (PMID 22487062, 2012). "Furthermore, DKK-1 seems to induce the proliferation of human adult bone marrow stem cells and contribute to the control of osteoporosis, as mutations in LRP5 that impede binding of DKK-1 are responsible for high bone density." (PMID 21029453, 2010). "In summary, the discovery almost a decade ago that mutations in LRP5 were causally associated with alterations in bone mass has stimulated numerous lines of research that have identified a number of promising targets to treat osteoporosis." (PMID 20948575, 2010). "Actually, LRP5 genetic polymorphisms might cause loss of function of LRP5, decrease the signaling activity of the canonical Wnt signaling pathway, and lead to reduced bone formation, thereby conducing to the development of bone fracture and osteoporosis." (PMID 25580429, 2014). "One of the major superiorities may be that the present research shed lights on the relation of genetic polymorphisms in LRP5, especially the rs3736228 C>T variant, and the increased susceptibility to bone fracture and osteoporosis, comprehensively and systematically." (PMID 25580429, 2014). "To investigate whether allelic variations of the LRP5 gene contribute to bone mass and osteoporosis in Tunisian population, we studied the association of Ala1330Val and Val667Met polymorphisms with BMD variation and osteoporosis risk in 566 Tunisian post-menopausal women." (PMID 24885293, 2014). "Inactivating mutations in LRP5 cause Osteoporosis-Pseudoglioma Syndrome (OPPG), presenting with early-onset osteoporosis and blindness." (PMID 41393297, 2025). "Sclerostin, an osteocyte-specific glycoprotein that inhibits the canonical Wnt pathway (similarly to DKK1 by binding to LRP5/6) is the target of romosozumab, the humanized monoclonal antibody treatment for osteoporosis." (PMID 40700291, 2025). "It shows that natural variations in key Wnt pathway genes (LRP5 and AXIN1) directly influence a person’s risk of developing osteoporosis." (PMID 41282593, 2025). "Notable loci, including SOST and LRP5, have deepened our understanding of osteoporosis genetics and informed therapeutic advancements, such as sclerostin inhibitors and WNT modulators." (PMID 40411668, 2025). "The crispant model has been compared with a stable lrp5 knockout zebrafish model to demonstrate the suitability of crispants for the functional validation of osteoporosis candidate genes." (PMID 39791729, 2024). "The inactivating mutation of LRP5 causes osteoporosis pseudo glioma syndrome (OPPG), characterized by early-onset osteoporosis, low bone mineral density, and blindness." (PMID 39295699, 2024). "Identifiable risk factors include a low body mass index (BMI), reduced physical activity during adolescence, a strong family history of osteoporosis, and genetic variations in the LRP5 and WNT1 genes." (PMID 39703866, 2024). "Several large GWAS have investigated the genetics of osteoporosis, revealing BMD-associated genes, including ESR1, LRP4, ITGA1, LRP5, SOST, SPP1, TNFRSF11A (RANK), TNFRSF11 (RANKL), and TNFRSF11B (OPG)." (PMID 39769358, 2024). "This study focuses primarily on pathogenic or rare suspicious variants in low-density lipoprotein receptor-related protein 5 (LRP5), plastin 3 (PLS3), or proto-oncogene Wnt-1 (WNT1) as monogenic causes of osteoporosis." (PMID 37277619, 2023).